CEP41 (centrosomal protein 41)
Description:
Required during ciliogenesis for tubulin glutamylation in cilium. Probably acts by participating in the transport of TTLL6, a tubulin polyglutamylase, between the basal body and the cilium.
Synonyms: TSGA14; DKFZp762H1311; FLJ22445; JBTS15
Tractability: PROTAC: its protein half-life has been measured.
Gene: Protein-coding gene on chromosome 7 (130,393,771 to 130,442,433, reverse strand). Ensembl gene ENSG00000106477.
Subcellular location: Cytoplasm, cytoskeleton, microtubule organizing center, centrosome; Cell projection, cilium; Cytoplasm, cytoskeleton, cilium basal body
Subcellular location (Human Protein Atlas): Primary cilium; Basal body
Pathways (Reactome):
Cell Cycle: AURKA Activation by TPX2; Loss of Nlp from mitotic centrosomes; Loss of proteins required for interphase microtubule organization from the centrosome; Recruitment of NuMA to mitotic centrosomes; Recruitment of mitotic centrosome proteins and complexes; Regulation of PLK1 Activity at G2/M Transition
Organelle biogenesis and maintenance: Anchoring of the basal body to the plasma membrane
Gene Ontology:
Molecular function: protein binding
Biological process: cilium assembly; protein polyglutamylation
Cellular component: centriole; centrosome; ciliary basal body; cilium; membrane; cytosol
Genetic constraint (gnomAD): Loss-of-function variants: 15 observed, 21.67 expected, observed/expected ratio (o/e) 0.69, 90% interval 0.46 to 1.07. The upper end of that interval is the gene's LOEUF score, 1.07, which puts it in group 4 of 6, group 1 being the genes least tolerant of losing a copy. Missense variants: 300 observed, 340.15 expected, observed/expected ratio (o/e) 0.88, 90% interval 0.8 to 0.97. Synonymous variants: 114 observed, 133.84 expected, observed/expected ratio (o/e) 0.85, 90% interval 0.73 to 1.
Gene-disease validity (ClinGen):
ClinGen rates the evidence that CEP41 causes each of these diseases.
ciliopathy (autosomal recessive): Strong. A genetic disorder of the cellular cilia or the cilia anchoring structures, the basal bodies, or of ciliary function.
Homologues: Orthologues: chimpanzee CEP41 (99% identical), macaque CEP41 (91% identical), guinea pig Cep41 (90% identical), pig CEP41 (88% identical), dog CEP41 (87% identical), mouse Cep41 (87% identical), rabbit CEP41 (86% identical), rat Cep41 (75% identical), tropical clawed frog cep41 (60% identical), zebrafish cep41 (58% identical). Paralogues in human: TSTD1 (7% identical).
Diseases named in the same sentence as CEP41 in open-access papers:
CEP41 is named in the same sentence as 11 diseases in open-access papers, as found by Europe PMC text mining. Sharing a sentence is not in itself a finding about the gene and the disease. The quoted sentences say what the papers report.
ciliopathy (5 papers, 2015 to 2021). "Depletion of CEP41 in zebrafish and mice causes similar defects in axoneme glutamylation and ciliopathy-related phenotypes." (PMID 33748109, 2021). "For most proteins, the trend reflected results from the WCP (i.e. PLK4 is up‐, whereas CEP63 and CEP57 down‐regulated) with the ciliopathy‐associated proteins CEP41 and CENPF being notable exceptions." (PMID 31304626, 2019). "We were able to reclassify a miscellaneous case within the ciliopathy group owing to the identification of a novel homozygous likely causal CEP41 variant." (PMID 29588463, 2018). "The involvement of CEP41, first in the ciliopathy JBTS and now with our study in ASD, points toward gene dosage and variant-specific effect as factors that determine the phenotype." (PMID 30664616, 2019). "Furthermore, as JBTS ciliopathies, including the CEP41 subtype, are characterized by distinctive cerebellar malformation signature (i.e. molar tooth sign), the individuals with ASD and CEP41 heterozygous mutations should be investigated with neuroimaging to evaluate for structural CNS abnormalities." (PMID 30664616, 2019). "However, as defective axoneme acetylation is not observed in CEP41- or ARL13B-deficient cells, we reason that defective axoneme glutamylation is probably the major driver for the development of ciliopathy phenotypes observed in Joubert syndrome patients." (PMID 33748109, 2021).
Joubert syndrome (5 papers, 2013 to 2025). Joubert syndrome (JS) is characterized by congenital malformation of the brainstem and agenesis or hypoplasia of the cerebellar vermis leading to an abnormal respiratory pattern, nystagmus, hypotonia, ataxia, and delay in achieving motor milestones. "Shortly after the characterization of CEP41 as a Joubert syndrome protein, homozygous mutations in TTLL5 were reported to cause retinal dystrophy in a subset of patient families with inherited retinal degenerations." (PMID 33748109, 2021). "Homozygous gene-disrupting variants in CEP41 were initially found to be responsible for recessive Joubert syndrome." (PMID 30664616, 2019). "Notably, mutations in CEP41 that disrupt splice site selection and protein function have been linked to Joubert syndrome." (PMID 40288647, 2025). "Given that mutation in CEP41, another Joubert syndrome protein, also leads to defective ciliary entry of tubulin glutamylase TTLL69, hypoglutamylation-induced signaling defects may be a key factor contributing to the pathogenesis of Joubert syndrome." (PMID 30120249, 2018).
autism (2 papers, 2019). Persistent deficits in social interaction and communication and interaction as well as a markedly restricted repertoire of activity and interest as well as repetitive patterns of behavior. "Zebrafish also demonstrated its rapid disease-modeling capability in a recent study in which a novel autism risk gene, CEP41, was identified by whole-exome sequencing." (PMID 31413047, 2019). "The zebrafish CEP41 morphant showed deficits in social preference behavior, providing experimental support for this new autism risk gene." (PMID 31413047, 2019). "Although we identified the association of CEP41 with ASD, our study design did not provide evidence for association of a specific candidate gene with autism in 25 out of 26 families." (PMID 30664616, 2019).
Infertility (1 paper, 2024). "Infertility with normal sperm count was predicted by CEP41 hypermethylation (OR = 1.750, 95% CI 1.038–2.950) and hypermethylation of both CEP41 and GNASAS (OR = 2.389, 95% CI 1.137–5.021)." (PMID 39017772, 2024). "Despite limitations such as the scarcity of CpG sites in methylation analysis, our study is the first to demonstrate hypermethylation of GNASAS and CEP41 in spermatozoa and to demonstrate the variable relationship between DNA methylation and gene expression in infertile men." (PMID 39017772, 2024). "Multinomial logistic regression analysis was performed to predict infertility with hypermethylation of GNASAS and CEP41." (PMID 39017772, 2024). "We demonstrated that CEP41 hypermethylation alone and in combination with GNASAS hypermethylation is a marker for assessing infertility with normal sperm count." (PMID 39017772, 2024). "On the other hand, for assessing oligozoospermic infertility, CEP41 hypermethylation did not increase the predictive value of GNASAS hypermethylation." (PMID 39017772, 2024).
Koolen-de Vries syndrome (1 paper, 2018). A chromosomal anomaly characterized by developmental delay, childhood hypotonia, facial dysmorphism, and a friendly/amiable behavior. "Notably, clinical refinement of complex phenotypes was achieved in 4 cases, including 2 de novo OTX2-related syndromes, a novel phenotypic association for the ciliary CEP41 gene, and the co-existence of biallelic USH2A variants and a Koolen-de-Vries syndrome–related 17q21.31 microdeletion." (PMID 29588463, 2018).
male infertility (1 paper, 2024). The inability of the male to effect fertilization of an ovum after a specified period of unprotected intercourse. "Although CEP41 is highly expressed in human testis, the association with male infertility remains unknown." (PMID 39017772, 2024). "A better understanding of sperm GNASAS and CEP41 hypermethylation could advance innovative diagnostic markers for male infertility." (PMID 39017772, 2024).
cancer (2 papers, 2018 to 2020). A tumor composed of atypical neoplastic, often pleomorphic cells that invade other tissues. "Finally, our findings suggesting an essential role of CEP41 in tumor angiogenesis provide novel insight into the development of cancer therapeutics targeting CEP41 or ciliary tubulin glutamylation." (PMID 31885126, 2020). "We thus asked whether under cancer cell‐induced hypoxic conditions, CEP41 influences EC dynamics to induce tumor angiogenesis in vivo." (PMID 31885126, 2020).
tumor (1 paper, 2020). "These in vivo results indicate an essential role for CEP41 in tumor angiogenesis that is likely attributable to its activation of HIF1α in ECs under hypoxic conditions." (PMID 31885126, 2020). "We here find that CEP41 facilitates hypoxia‐induced angiogenesis through HIF1α‐AURKA‐VEGF pathway in vitro and further show that CEP41 affects EC dynamics under tumor‐induced hypoxic conditions in vivo." (PMID 31885126, 2020).
CEP41 also shares sentences with these, for which no sentence is quoted: Macrocephaly (1 paper); microcephaly (1); retinal diseases (1).